MIR6772 (microRNA 6772)
Synonyms: hsa-mir-6772
Gene: MicroRNA gene on chromosome 16 (57,772,289 to 57,772,352, reverse strand). Ensembl gene ENSG00000274816.
Homologues: Orthologues: chimpanzee MIR6772 (100% identical).